IL18BP (interleukin 18 binding protein)
Diseases named in the same sentence as IL18BP in open-access papers (continued):
Sharing a sentence is not in itself a finding about the gene and the disease.
cancer (16 papers, 2013 to 2025). A tumor composed of atypical neoplastic, often pleomorphic cells that invade other tissues. "Accordingly, it is crucial to comprehend the processes governing the regulations of IL‐18 and IL‐18BP in cancer and microbial infections." (PMID 39188114, 2024). "Recent studies have primarily focused on the involvement of IL‐18 and IL‐18BP in the regulation of immune responses in cancer and microbial infections." (PMID 39188114, 2024). "We found that ccRCC tumors express high levels of both IL-18 receptor subunit genes and the secreted blocking protein IL18BP relative to other cancer types." (PMID 39561007, 2024). "Compugen believes that blocking IL-18BP with an antibody represents a promising approach in leveraging cytokine biology in cancer treatment." (PMID 39769266, 2024). "A recent study demonstrated that IL-18BP is highly expressed in various cancers, including clear cell RCC (ccRCC) and that it functions as a secreted immune checkpoint in cancer." (PMID 39561007, 2024). "Although viruses and cancer cells have granted the benefit of this inhibitory role of IL-18BP to increase Treg cells, and thus evade immune system recognition." (PMID 35885055, 2022). "On the other hand, IL-18 is highly expressed in several cancers, within its microenvironment IL-18BP acts as a barrier for the cancer niche not only by increasing Treg, but also by attenuating natural killer (NK)-mediated killing." (PMID 35885055, 2022). "Due to a potential role of IL-18 in cancer progression and metastasis, an IL18BP-Fc has been developed to antagonize the effects of IL-18." (PMID 28391240, 2017). "Conversely, in conditions where immune responses are suppressed, such as cancer, strategies to inhibit IL-18BP and boost IL-18 activity might be more appropriate." (PMID 39769266, 2024). "IL-18BP is highly expressed in numerous cancers, including ccRCC." (PMID 39561007, 2024). "Lassen Therapeutics’ anti IL-18BP antibody is a candidate for human cancer immunotherapy." (PMID 39769266, 2024). "In addition to the upregulation of IL-18BP in inflammatory conditions IL-18BP is upregulated in various cancer types, such as breast, pancreas, prostate, and ovarian." (PMID 35885055, 2022). "Therefore, it has been suggested that the elevated secretion of IL-18BP by PCa cells indicates the effort of cancer cells to overcome immune surveillance." (PMID 33507690, 2021). "Therefore, IL-18BP has been suggested as an immunotherapy potential target for many cancers." (PMID 35885055, 2022). "Therefore, it would be important to know whether IL-18BP level is sufficient to counteract the pleiotropic effects of IL-18 in the different stages and clinical conditions of cancer patients." (PMID 24963217, 2014). "Compugen employed its proprietary computational discovery platform to identify new drug targets with the ability to enhance anti-cancer immune responses and selected the COM503 anti IL-18BP antibody aimed for the treatment of solid tumors." (PMID 39769266, 2024). "Nevertheless, many studies show that the use of IL18 binding protein (IL18BP, a soluble protein that binds to IL18), which will neutralize the effects of this interleukin, may have a positive therapeutic effect on cancer." (PMID 36012171, 2022). "There were eight favorable prognostic genes and six poor prognostic genes incorporated in this signature, and a variety of OSRGs such as CD38, FOXO1, HGF, IL18BP, and TRPM2 were closely involved in the previous studies regarding cancer subtypes and immune landscape." (PMID 36561981, 2022). "Also, we reported that IL-27, similar to IFN-γ, induces the expression of IL-18BP, IDO and PD-L1 immune regulatory molecules in human cancer cells." (PMID 27683036, 2016). "The majority of studies on serum IL-18 levels in cancer patients do not provide concomitant information about the concentration of its antagonist, that is, IL-18BP or IL-18-inducible cytokines such as IFN-γ in the same blood samples." (PMID 24963217, 2014).
infection (15 papers, 2010 to 2025). The state of being infected such as from the introduction of a foreign agent such as serum, vaccine, antigenic substance or organism. "In line with the previous findings, our gene profiling on DCs upon NK depletion under Cm infection also indicates the upregulated genes related to type II cytokines and signaling such as Il33, Il9b, and Il18bp." (PMID 40332391, 2025). "Prf1 KO and BL/6 WT control mice were infected with MCMV and treated with 10 μg of IL-18BP or vehicle starting 84 h after infection." (PMID 22891066, 2012). "Additionally, IL18BP, an antagonist of IL-18 (an important member of the IL-1 super family of cytokines), was also up-regulated after infection, supporting the observation that ASFV infection suppresses IL-1 and IL-18 signaling." (PMID 31725732, 2019). "However, infection of AAV8-Il18bp could increase the IL-18BP mRNA level more than the AAV8-Luc group (p < 0.05)." (PMID 36551229, 2022). "Prf1 KO mice were infected with 1 × 106 PFU of in vitro-derived DN-SCP-MCMV and starting 84 h after infection, mice received DOX, IL-18BP, or a combination of both." (PMID 22891066, 2012). "IL-18BP displays a high affinity for IL-18 (Kd 399 pM) and is present in the serum of healthy subjects at 20-fold molar excess to IL-18 to blunt the TH1 response to foreign organisms and reduce autoimmune responses to routine infection." (PMID 25699211, 2015). "The up-regulated genes EFNA1 and IL18BP were not significantly modulated in the challenge infection data set." (PMID 20950493, 2010). "To learn more about the function of IL-18BP in our study, we constructed an AAV-8 vector carrying Il18bp and the liver-specific promoter TBG, which could specifically target liver tissue for infection and could stably express the target gene for more than six months." (PMID 36551229, 2022).
head and neck tumors (1 paper, 2024). "In this study, it was found that IL-1α, IL-1β, IL1R1, IL1RL1, IL1F10, IL33, CASP1, and AIM2 were highly expressed in head and neck tumors, while IL1RN, IL1RAPL1, IL1RAPL2, IL18BP, IL18R1, and IL18RAP were low in expressed, which is consistent with previous literature." (PMID 39461030, 2024).
heart diseases (1 paper, 2023). "Interleukin-18-binding protein, (IL-18) is a member of the IL-1 family of cytokines and increasing numbers of clinical studies indicate a role for IL-18 in heart diseases." (PMID 36720768, 2023).
infectious disease (1 paper, 2016). A disorder directly resulting from the presence and activity of a microbial, viral, or parasitic agent in humans. "The development of MAS can be triggered by infectious diseases of viral or bacterial etiology and has been associated with exceptionally high serum levels of free IL-18 with concomitant hyperferritinemia, reflecting an IL-18/IL-18BP imbalance." (PMID 27977798, 2016). "This demonstrates that special attention should be paid to circulating levels of free IL-18 molecules when studying the IL-18 response in infectious diseases, particularly because the ELISA kits for IL-18 detection measure the mature form of the cytokine, both free and complexed with IL-18BP." (PMID 27977798, 2016).
liver (1 paper, 2026). "Phages, antibiotic, and co-housing experiments revealed that specific gut microbiota featuring Il18bp-/- mice is implicated in their exacerbated liver inflammation and fibrosis status." (PMID 41480237, 2026).
IL18BP also shares sentences with these, for which no sentence is quoted: diabetes (3 papers); inflammatory bowel disease (3); haemophagocytic syndrome (2); idiopathic thrombocytopenia purpura (2); metabolic disease (2); acute kidney injury (1); AIDS (1); amyotrophic lateral sclerosis (1); atopic dermatitis (1); autoimmune disorders (1); bacterial infections (1); Behcet disease (1); benign breast disease (1); brucellosis (1); bullous pemphigoid (1); celiac disease (1); chronic obstructive pulmonary disease (1); connective tissue disorder (1); endothelial dysfunction (1); Graves disease (1); hematologic malignancy (1); hepatitis C (1); Hypertension (1); idiopathic pulmonary fibrosis (1); inflammation (1); juvenile idiopathic arthritis (1); kidney cancer (1); leptospirosis (1); metabolic syndrome (1); neuropathic pain (1).
A further 7 diseases each share a sentence with IL18BP in 1 paper.